IL10 (interleukin 10)
Diseases named in the same sentence as IL10 in open-access papers (continued):
Sharing a sentence is not in itself a finding about the gene and the disease.
infection (continued). "M09 cells did not expand to higher levels on day 20 when administering αlL-10R from the time of initial infection, suggesting IL-10 does not regulate their late-rising phenotype, albeit IL-10 deficient mice show enhanced expansion of other MCMV-specific CD4 T cells." (PMID 38236791, 2024). "IL-10 has been reported to counteract an exacerbated immunopathology induced by a high magnitude of Th1 immune response and accelerate the wound healing process, at the same time, playing a role in the progression of the infection and parasite persistence in CL." (PMID 39364404, 2024). "Correlation analyses were conducted to examine the relationship between cytokines (IL-6 and IL-10) and biochemical parameters (platelets, white blood cell count, and liver transaminases), including individuals in the two phases and with both types of infection." (PMID 39457019, 2024). "Therefore, IL-10 has a major influence on the course of infection in these mice." (PMID 38535182, 2024). "IL-10 secreted at the site of ongoing inflammation is responsible for maintaining the right balance between effective pathogen elimination and prevention of detrimental immune-mediated response against infections, resulting in the restoration of normal tissue homeostasis." (PMID 37359549, 2023). "Studies show that IL-10 plays an important role in regulating immune response to infectious agents by suppressing the secretion of pro-inflammatory cytokines and thereby impairing the elimination of pathogens, leading to persistence and worsening of the infection." (PMID 36897879, 2023). "A prospective study that included 756 pediatric HLH patients found that a specific cytokine pattern with significantly elevated levels of IFN-γ and IL-10 and only moderately elevated levels of IL-6 had high diagnostic accuracy for HLH and could be used to differentiate HLH from infection." (PMID 37512867, 2023). "Therefore, the comparison between mice strains shows that BALB/c mice have higher values of the proinflammatory cytokines (IFN-γ and IL-6) and the anti-inflammatory cytokines (IL-10 and IL-4) in response to infection than C57BL/6 mice (Welch two-sample t test, P < 0.05)." (PMID 37140369, 2023). "Therefore, we hypothesized that infection of IL-10−/− mice with P. chabaudi would lead to increased neuronal activity through the TNFR1–JAK2–FGF14–Nav1.6 signaling network." (PMID 38115011, 2023). "IL-10 could limit the activation of innate and adaptive immune cells to maintain homeostasis and protect the host from immune pathological damage, autoimmune damage, and allergic reactions induced by infection." (PMID 38111733, 2023). "In addition, IL-10-producing B cells were found to contribute to host defense against infections." (PMID 37759658, 2023). "However, in contrast to symptomatic disease, which is characterized by more polarised production of inflammatory mediators, virus-specific T-cell responses in asymptomatic infection are characterized by the balanced secretion of inflammatory cytokines such as IL-10 and IL-6." (PMID 36679947, 2023). "This pattern could be related to the expression levels of the anti-inflammatory cytokine IL-10, which reaches its peak of overexpression at 6 and 9 h post infection, revealing that it could be acting as a negative regulation mechanism of the inflammatory response in a second modulation phase." (PMID 37629124, 2023). "Additionally, epithelial cells can produce IL-10 in response to tissue damage or infection." (PMID 37626658, 2023). "Hence high expression of TNF-α and low expression of IL-10 may result in the low infection rates in this patient population." (PMID 37428723, 2023). "Future directions should include further optimization of the α-IL-10 doses, determining whether other anti-inflammatory mediators impact survival, and investigating whether additional gene pathways are impacted by burn and infection." (PMID 37929965, 2023).
infection (continued). "Thus, it was of interest to determine if the increase in parasite burden and lag in parasite clearance observed in Bhlhe40−/− mice was due to elevated IL-10 production, particularly by CD4+ T cells, given their role in IL-10 production in response to this infection." (PMID 37843306, 2023). "Therefore, the IL-10 production induced in CD4+ T cells by IgG from asymptomatic carriers may collaborate with a clinical control of the disease or infection control on patients submitted to therapeutic protocols." (PMID 37711742, 2023). "Individuals with polymorphisms in loci containing IL6, IL10, FCN2, RNASE3 and multiple Th17 pathway genes such as IL12B and IL17B had varying worm burden, indicating that these loci may play a role in determining infection intensity." (PMID 38033168, 2023). "Also, other transcription factors could serve to downregulate IL-10 expression at later times after infection; however, the identity of these transcription factors is unclear." (PMID 37843306, 2023). "In the present study, IL-6 and IL-10 mRNA expressions were increased via PCV2b infection in NPTr and iPAM 3D4/21 cells in accordance with previous studies reporting up-regulation of IL-6 in epithelial cells and increased levels of IL-6 and IL-10 in porcine alveolar macrophages (PAMs)." (PMID 37243291, 2023). "Collectively, results of the IL-10R blockade study showed that IL-10 plays a role in attenuating the level of lung inflammation, as well as in decreasing CD4+ T cell proliferation and the Th1 response in B cell-deficient mice during the chronic phase of infection." (PMID 36888692, 2023). "Importantly, PB-PCs do not inherently produce IL-10 at steady state, but they may be induced to produce IL-10 by inflammatory environments present during infection or disease." (PMID 38155972, 2023). "Our study found that IL-6 and IL-2 were increased significantly, while IL-10 was decreased in the Wheeze group, indicating that anti-(pro-)inflammatory factors imbalance may play a critical role in the occurrence and development of wheezing after infection." (PMID 36691058, 2023). "The expression and activity of IDO1 during infection were maintained stably greater at night than during the day in CF mice, as well as levels of Foxp3, Il10 and Tgfb gene expression, which may explain the reduced inflammatory damage and PMN recruitment in mice infected at ZT12." (PMID 36896128, 2023). "The T-cell response may only provide limited protection, with the suppressive environment in the testes likely favoring the anti-inflammatory pathway with constitutive expression of IL10 and TGFβ, but perhaps this limits the infection sufficiently to allow testicular macrophages time to act." (PMID 36799886, 2023). "However, the molecular mechanism underlying infection by Leishmania species-induced enhancement of the stability of IL-10 mRNA in NK cells is not clear, and additional studies are needed to determine if similar mechanisms exist in NK cells." (PMID 36776864, 2023). "This might be a result of IL-10’s anti-inflammatory properties, which stop the natural killer and T cell activities from having an impact on the intense inflammatory response following the initial infection." (PMID 36882862, 2023). "As IL-10 KO mice established an important role for the cytokine in promoting S. aureus persistence during craniotomy infection, as evident by significantly lower bacterial burden in the brain and galea at later stages of infection, this led us to evaluate the possible cellular sources of IL-10." (PMID 37179295, 2023). "Therefore, we investigated whether IL-10 produced during LD infection utilizes the same pathway to upregulate TIM-3 expression on DCs." (PMID 37202419, 2023). "However, the pathophysiological roles of IL-10 in infection-induced EM remain to be elucidated." (PMID 36719648, 2023).
infection (continued). "Considering that prior work in salmonids often, but not always, find significant upregulation of IL-10 following infection from myxozoans and that both myxozoans were detected at 100% prevalence at 14 and 21 dpd, it seems plausible these patterns are in part due to infection." (PMID 37649642, 2023). "In experimental infection caused by L. infantum, type I IFNs (IFN-α and IFN-β) produced during parasite recognition via sequential signaling mediated by TLR4/TRIF/IRF-1 suppress the development of Th1 responses via mechanisms depending on IL-10, which contributes to antigen persistence." (PMID 35585983, 2022). "Furthermore, it moderately increased the expressions of proinflammatory cytokines including IL-1β, IL-6, and TNF-α in the early stage of infection and decreased their release rapidly in the later stage, while regulated the same phase change of anti-inflammatory cytokine IL-10." (PMID 35071595, 2022). "These and other cytokines involved in the immunopathology of acute patients such as IL-1β and IL-10 could be fundamental for the discrimination of the outcome of the infection as they have been seen to be significantly higher in severe than in mild forms of the disease." (PMID 36079033, 2022). "A separate study using Plasmodium yoelii demonstrated that although Rag-/- mice engrafted with WT as opposed to IL-10-deficient CD4+ T cells had increased parasitemia following infection, these mice experienced less severe weight loss and a modest improvement in survival duration." (PMID 36389662, 2022). "Whereas in late post-infection times keratinocytes produce IL-10, which could mediate an anti-inflammatory response and therefore aid in the survival of the pathogen, it could also eventually contribute to a protective effect for the host by decreasing hyperinflammation." (PMID 35628694, 2022). "Each of these characteristics may be available at bedside in parallel of the assessment of infection, organ dysfunction, pro- (for example TNFα and/or IL-18) and anti-inflammatory (for example IL-1Ra and/or IL-10) cytokines, and markers of adaptive function (for example HLA-DR)." (PMID 36301921, 2022). "Therefore, this review aims at summarizing the current knowledge on the roles of MIF and IL-10, which can be considered as a molecular “Yin-Yang” in the modulation of the host immune microenvironment during infection, and particularly during African trypanosomosis." (PMID 35464430, 2022). "Whereas the binding to DC-SIGN could be a strategy used by leptospires to dampen the DC activation and enhance the expression of IL-10, an anti-inflammatory cytokine that has been shown to be instrumental for successful infection by leptospires and renal colonization, remains to be characterized." (PMID 35812397, 2022). "Indeed, a longitudinal analysis of children from an endemic region of Mali indicates that a recent exposure to Plasmodium changes the cytokine profile of a subsequent Plasmodium-infection, specifically upregulation of IL-10 in children with persistent asymptomatic infection." (PMID 36146602, 2022). "Importantly however, IL-10 also affects the nuclear factor kappa B (NFκB) transcription factor pathway, a key signaling pathway with an established role in the mediation of inflammation and a response to tissue damage and/or infection." (PMID 36290283, 2022). "However, IL-27 also promotes IL-10 production, (reviewed in a later section) which could downregulate IFNγ production later during infection to mediate immunopathology." (PMID 35634328, 2022). "Our data so far had shown that IL-10 expression and IL-10 receptor expression were both concentrated at the site of infection and suggested that the primary T cell target of IL-10 signalling during H. polygyrus infection may be Th1 cells in the small intestine." (PMID 35428872, 2022).
infection (continued). "IL-10, on the other hand, reported to modulate the balance between the clearance of pathogen and immunopathology while the lack of this cytokine increases resistance to Brucella infection and its early induction in B. abortus-infected monocytes favors infection." (PMID 36039381, 2022). "However, cytokine levels at 75 dpv were lower than those at 30 dpv, which may be due to the activation of the anti-inflammatory response, as evidenced by the increased levels of IL-10 in mice vaccinated 30 days after infection." (PMID 35986017, 2022). "Furthermore, increased CD4+IL-10+ was observed in the lungs in comparison to the Infection group." (PMID 36119106, 2022). "Likely, the elevated plasma IL-10 (optimal threshold >11.59 pg/mL) inhibits antigen presentation, decreasing ex vivo LPS-stimulated TNF-α production capacity (optimal threshold < 505.8 pg/mL) leaving the individual highly susceptible to infections by decreasing T cell immunity." (PMID 35958579, 2022). "The expression of IL10 and MR was not modulated upon infection with all variants." (PMID 36601113, 2022). "Therefore, following gut microbiota depletion IL-10−/− mice were challenged with 109 viable C. jejuni cells by oral gavage and treated with butyrate via the drinking water (22 g/L) starting on day 2 post-infection." (PMID 36296229, 2022). "Guan found that IL-6 and IL-10 were closely related to bloodstream infection and suggested that IL-10 might distinguish G- and G+ infection, but the diagnostic effect of IL-10 was not ideal, with a sensitivity of 64.1%." (PMID 35432366, 2022). "However, by conducting this protective role, IL-10 could also lead to high parasite-density infections with the development of other complications, such as accumulation of parasitized RBCs in tissues leading to hypoxia and vasculature damage." (PMID 35464430, 2022). "In addition, jejunal IL-10 and sIgA concentrations were down-regulated after NE infection as compared with the CON group, which could be increased by 600 mg/kg of TA supplementation (P < 0.05)." (PMID 35387091, 2022). "In addition, a pattern of reduction in CSF IL-10 levels was also seen post-infection." (PMID 35130924, 2022). "Therefore, the IL-10 produced by the host during these infections could act in synergy with the intrinsic ability of these pathogens to undermine the immune response, thereby further promoting bacterial proliferation and dissemination." (PMID 35464430, 2022). "Guan’s study did not observe the significance of the combination of IL-6 and IL-10 for the differentiation of G- and G+ infection, which may be caused by factors such as the different types of diseases of the study subjects." (PMID 35432366, 2022). "A possible overproduction of IL-10 in HIV patients with a down-regulation of Th1 responses and an inhibition of various macrophage functions might contribute to the increased susceptibility to infections with various parasites, bacteria, and viruses." (PMID 36678367, 2022). "IL-10 can directly attenuate inflammatory profile of DC and macrophages by an autocrine mechanism, as well as reduce the excessive proinflammatory responses as part of a negative-feedback mechanism to limit an overactive immune response in tissues during infection." (PMID 35723745, 2022). "Since IL-10 and TGF-β polarize macrophages toward an anti-inflammatory phenotype, we analyzed their impact on porcine monocyte-derived macrophages’ (moMΦ) susceptibility to infection and their responses to two genotype I ASFV strains, virulent 26544/OG10 and attenuated NH/P68." (PMID 35215110, 2022). "Decreased interleukin 10 (IL-10) and IL-1R levels are in turn associated with increased activation of CD8+ T cells, which may promote infection in HIV-exposed individuals." (PMID 36339339, 2022).
infection (continued). "Our analysis of M.tb infection at 60 days post infection, suggests that IL-10 production by T cells and production of IL-27 by macrophages will further expand differentiation of Tr1 cells, which eventually leads to decreased ability of stressed old mice to control the infection." (PMID 36189368, 2022). "The seemingly surprising disease-promoting role of IL-10 in MA-ARDS may represent an imbalance between its cardinal role in preventing immunopathology during infection, and its concomitant inhibition of microbial control resulting in bacterial outgrowth and dissemination." (PMID 35768411, 2022). "However, IL-10 does not appear to have any diagnostic value for the development of post-traumatic infection in this study." (PMID 34568354, 2021). "Also, IL-10 producing DCs were increased during Cl 13 infection." (PMID 34696381, 2021). "In fact, within six days following peroral C. jejuni infection, microbiota-depleted IL-10−/− mice did not only display high pathogen loads in their intestinal tract, but also suffered from wasting and bloody diarrhea indicative for acute enterocolitis and succumbed to infection." (PMID 33466708, 2021). "Also, B. abortus triggers the anti‐inflammatory IL‐1041, 42, 43 and, interestingly, activated macrophages function by IFN‐γ formation toward Brucella‐like bactericidal capacity as well as the construction of pro‐inflammatory mediators were suppressed by IL‐10 during infection." (PMID 34449979, 2021). "Thus, despite multiple potential cellular sources of IL-10, GC B cell, GC-TFH cell and parasite-specific antibody impairments observed in Plasmodium-infected mice treated with α-IL-10R antibody were phenocopied by infection of mice harboring Il10-/- CD4 T cells." (PMID 33529242, 2021). "Furthermore, let-7 family miRNAs could directly modulate the expression of key immunoregulatory cytokines including il-6 and il-10, which hinted the downregulation of these miRNAs could increase the levels of these cytokines upon infection." (PMID 34222406, 2021). "In turn, high IL10 was observed with mycobacterial persistence suggesting that in particular the ratio of these cytokines might reflect the immunological burden of infection." (PMID 33767693, 2021). "Furthermore, IL-10-mediated increased NK cell cytotoxicity has been suggested to facilitate antigen uptake from dead cells by antigen presenting cells and thereby enhancing the cross-talk between the innate and the adaptive immune system during infection." (PMID 33679785, 2021). "However, as teleost fish IL-10 demonstrates immune suppressive function, il-10 expression upon pathogen infection could be the natural way of lumpfish to regulate its early innate immune responses." (PMID 34880856, 2021). "Although IL-12 and IL-10 are considered essentially antagonistic, under the context of Brucella infections, both cytokines may work in concert to limit the progression of the infection." (PMID 34576830, 2021). "Interestingly, a study about acute HBV infection in a human cohort, identified a peak of IL10 serum level within the viremia phase of infection, suggesting that once hepatic tolerance prevailed, HBV viremic phase starts, followed by symptomatic disease progression." (PMID 32632817, 2021). "Infection with the toxigenic strain of S. hyicus induced both an inflammatory reaction and an anti-inflammatory response as indicated by the cytokine assay results—a significant increase in the levels of a pro-inflammatory cytokine (IL-1β) and an anti-inflammatory cytokine (IL-10)." (PMID 33665221, 2021). "In addition, a study using mouse models with tumor progression locus 2 (TPL2) or IL-10 knockout together with IFN signaling deficiency revealed that IL-10 induced by TPL2 signaling pathway might lessen host immune response and enhance SFTSV infection." (PMID 35087498, 2021).